IL10 (interleukin 10)
Diseases named in the same sentence as IL10 in open-access papers (continued):
Sharing a sentence is not in itself a finding about the gene and the disease.
tumor (continued). "Th1 cells release anti-tumor cytokines like interleukin (IL)-2, interferon (IFN)-γ, and tumor necrosis factor (TNF)-α, while Th2 cells release immunosuppressive IL-4, IL-5, IL-10, and IL-13." (PMID 40260236, 2025). "In contrast, in cancer, certain cytokines such as IL-10 and TGF-β suppress immune responses, allowing tumor cells to evade immune detection and promote tumor progression." (PMID 40364844, 2025). "Conversely, M2-like TAMs are driven by IL-4, IL-13, and IL-10, and promote tumor progression by releasing immunosuppressive factors (PGE2, TGF-β, IL-10), and pro-angiogenic mediators (FGF, PDGF, VEGF)." (PMID 41383623, 2025). "In summary, low expression of AGPAT3 in tumor cells facilitated the accumulation of LPA, which promoted the IL-6 and IL-10 expression of TAMs through LAPR signaling." (PMID 41502512, 2025). "The anti-tumor efficacy of antibiotics primarily depends on the reduction of IL-17A, this depletion results in an increase in anti-tumor T cells secreting IFN-γ within the tumor microenvironment and a decrease in pro-tumor T cells producing IL-17A and IL-10." (PMID 41403642, 2025). "Tumor exosomes containing miR-145 have been shown to downregulate HDAC11 in TAMs, unleashing IL-10 production and thereby promoting tumor immune evasion." (PMID 40358164, 2025). "Tumor cells secrete diverse chemokines that recruit macrophages and other inflammatory cells into the tumor stroma, where TAMs, in turn, release growth factors, cytokines, chemokines, and mediators such as VEGF, PDGF, IL-10, CXCLs, EGFR ligands, and FGFs." (PMID 41058699, 2025). "Another effect of MDSCs is the release of cytokines that promote inflammation and tumor progression, such as TNF-α, IL-10, and IL-1β, while they encourage invasion, migration, and metastasis via MMPs." (PMID 41369383, 2025). "•Cytokines like TGF-β and IL-10, along with chemokines such as CXCL12, establish an immunosuppressive microenvironment that promotes metastasis and tumor progression." (PMID 40242222, 2025). "Conversely, immunosuppressive cytokines like IL-10 and transforming growth factor-beta (TGF-β) inhibit cytotoxic immune responses and facilitate immune escape mechanisms, thereby promoting tumor growth and metastasis." (PMID 40612845, 2025). "Tumor cells also secrete immune-suppressive cytokines, such as IL-10, and can activate TGF-β, forming a network of immune-suppressive factors, further creating a conducive environment for tumor growth." (PMID 39996780, 2025). "The coordinated regulation of IL-10 and TGF-β1 family molecules offers crucial molecular evidence for understanding tumor immune microenvironment heterogeneity and guiding targeted interventions." (PMID 41438510, 2025). "IL-10, TGF-β, and IL-4 secreted from tumor cells drive the polarization of macrophages towards this pro-tumorigenic state." (PMID 39930476, 2025). "Within the tumor microenvironment, stromal and immunosuppressive barriers such as CAF- and MDSC-derived TGF-β and IL-10 secretion, ECM fibrosis, hypoxia, and metabolic competition continue to impair CAR-T trafficking, persistence, and function." (PMID 41348261, 2025). "Macrophages in the HCC TME are primarily polarized to the M2 phenotype, which secretes immunosuppressive cytokines like IL-10 and TGF-β, promoting tumor growth and suppressing anti-tumor T cell activity." (PMID 40034695, 2025). "Once localized to the tumor microenvironment, Tregs secrete immunosuppressive cytokines, including TGF-β and IL-10, which directly impair the cytotoxic function of CD8+ effector T cells, thereby facilitating tumor immune evasion." (PMID 40698080, 2025). "Pro-tumor cytokines like IL-10 and TGF-β promote an immune-evasive environment, while antitumor cytokines like IL-2 and TNF-α strive to elicit immune-mediated tumor destruction." (PMID 40309351, 2025). "IL-4 can activate M2-type macrophages, secrete IL-10, TGF-β, and CCL17, thereby inhibiting T cell-mediated anti-tumor immune responses." (PMID 40557160, 2025).
tumor (continued). "The levels of immune suppressive cytokines IL-10, TGF-β, and nitric oxide were also highly reduced, further showing low-dose CPX’s ability to shift the immune response phenotype to an anti-tumor, cell-mediated Th1 phenotype." (PMID 40650216, 2025). "Malignant ascites, common in advanced disease, contains immunosuppressive cytokines such as IL-10 and TGF-β, which dampen cytotoxic responses and facilitate metastatic tumor spheroid implantation." (PMID 41357243, 2025). "Conversely, M2 macrophages produce immunosuppressive factors such as IL-10 and VEGF, facilitating tumor growth, angiogenesis, and metastasis." (PMID 40297580, 2025). "• Higher IL-10 concentrations are observed in early-stage HCC (BCLC A), indicating an anti-inflammatory response at the onset of tumor development." (PMID 41379186, 2025). "Binding of C5a to C5aR1 on these immune cells promotes their migration into the tumor microenvironment, where they secrete immunosuppressive molecules, including reactive oxygen and nitrogen species (ROS/RNS) and interleukin-10 (IL-10)." (PMID 40806542, 2025). "This TME includes regulatory T cells (Tregs), myeloid-derived suppressor cells (MDSCs), and M2-polarized tumor-associated macrophages (TAMs), all of which release immunosuppressive factors like IL-10 and TGF-β to inhibit anti-tumor responses." (PMID 40034695, 2025). "The suppressive effect of TME on NK cytotoxic activity of NK cells can be mediated by cytokines such as TGF-β and IL-10, L-kynurenine, a product of tryptophan degradation, and prostglandin E2 (PGE2), secreted by tumor cells, suppressive immune cells, and CAFs." (PMID 40940764, 2025). "In contrast, when immunosuppressive factors (e.g., IL-10, TGF-β) accumulate in the microenvironment, B cells shift toward a pro-tumor phenotype." (PMID 41285707, 2025). "Tumor cells can reduce their immunogenicity by secreting immunosuppressive factors such as TGF‐β and IL‐10." (PMID 41179708, 2025). "In tandem, the secretion of immunosuppressive cytokines, such as IL-10 and TGF-β further compromises immune surveillance, fostering a tumor-supportive microenvironment that enables ongoing growth and metastasis." (PMID 40322886, 2025). "Cytokines including CCL-2, IL-6, IL-8, IL-10, IL-13, and TNF-α show tumor-specific secretion profiles, with experimental evidence demonstrating TIC-derived cytokines mediate immune evasion through recruitment and activation of MDSCs and TAMs." (PMID 40777043, 2025). "The TME promotes a phenotypic shift from M1 to M2 polarization through sustained exposure to IL-10, TGF-β, and other tumor-derived factors." (PMID 41142826, 2025). "Tumor‐derived factors such as TGF‐β and IL‐10 exacerbate NK dysfunction by dampening receptor expression and altering metabolic fitness." (PMID 40926366, 2025). "These macrophages exist along a functional spectrum, with M1 macrophages exhibiting tumor-suppressive properties, while M2 macrophages secrete pro-tumorigenic cytokines such as VEGF, IL-10, TGF-β, and HGF." (PMID 41357243, 2025). "Tregs can suppress effector T cell functions, such as those of CD8 + T cells, by secreting inhibitory cytokines like IL-10 and TGF-β and through direct cell interactions, thereby impairing their ability to recognize and eliminate tumour cells." (PMID 40591061, 2025). "Heat-inactivated OpdA significantly reduced metastasis, dependent on tumor-specific CD4+ and CD8+ T cells and IFN-γ, both locally and systemically, with decreased IL-10 levels suggesting a proinflammatory environment." (PMID 41019059, 2025). "M2 macrophages are characterized by their secretion of IL-10, PGE2, and TGF-β via the arginase pathway, promoting Th2 immune response and facilitating tumor progression and invasion in MM by inducing angiogenesis and suppressing the host’s immune response." (PMID 39953613, 2025).
tumor (continued). "In TAMs, phlorotannins reduced the expression of M2-like markers (CD163 and CD209) and decreased the secretion of IL-10, IL-17, and VEGF, all of which collectively support tumor progression." (PMID 41590709, 2025). "TAMs, especially those polarized to the M2 phenotype, secrete anti-inflammatory cytokines (e.g., IL-10, TGF-β) and growth factors that promote tumor growth, angiogenesis, and survival." (PMID 39897552, 2025). "Crucially, we have delineated the intricate crosstalk between tumor metabolism and immune regulation, revealing that the REL transcription factor mediates glycolytic metabolite-induced IL-10 production in M2-TAMs." (PMID 40959090, 2025). "Then M2 macrophages modulate the production and metabolic activity of immunosupressive cytokines, including IL-10 and transforming growth factor-β (TGF-β), thereby counteracting T cell-mediated tumor cytotoxicity." (PMID 40980688, 2025). "This activation promotes the secretion of interleukin-10 (IL-10) and transforming growth factor beta (TGF-β) by Treg, ultimately inhibiting the anti-tumor activity of T cells." (PMID 40276500, 2025). "The effector molecules of Breg cells, such as TGFβ, IL10, and IL35, can diminish effector T cell responses and/or promote Treg differentiation, thereby resulting in enhanced tumor progression." (PMID 41019045, 2025). "In most tumors, IL-10 and TGF-β are identified as immunosuppressive cytokines that increase tumor growth." (PMID 40722593, 2025). "This pathway promotes immune suppression by upregulating the secretion of cytokines such as IL-10 and TGF-β, and by inhibiting the cytotoxic functions of tumor-infiltrating immune cells." (PMID 41479886, 2025). "Tregs also secrete immunosuppressive cytokines, including IL-10 and TGF-β, which dampen the activity of effector immune cells and facilitate tumor growth." (PMID 40003906, 2025). "Functional assays show that SPON2 promotes OS cell proliferation, migration, invasion, and angiogenesis by enhancing the secretion of IL10, CCL2, and CSF1, which leads to M2 macrophage polarization and an immunosuppressive tumor microenvironment." (PMID 40730813, 2025). "In one study, Il-12 TRUCKs induced significant tumor infiltration by macrophages, albeit at the expense of a decrease of in CD8+ CAR-T cells, possibly via interleukin 10 (IL-10)-mediated immune suppression." (PMID 40861448, 2025). "M2c macrophages, induced by IL-10, TGF-β, and glucocorticoids, play a key role in immunosuppression and extracellular matrix remodeling, contributing to the tumor’s immune escape mechanisms." (PMID 40079009, 2025). "The relative abundance of Fusobacterium nucleatum and the expression levels of cytokine genes (IL-1β, IL-6, IL-10, IL-17, TNF) were measured in tumor and adjacent normal tissues to assess their differential expression and potential associations." (PMID 41267807, 2025). "In cancer, numerous studies have demonstrated that Bregs facilitate tumor immune evasion by secreting IL-10 and TGF-β and expressing PD-L1, thereby suppressing cytotoxic T and NK cell activity and contributing to tumor progression." (PMID 40861439, 2025). "Like MDSCs, TAMs also reduce the proliferation of anti-tumor cytotoxic T-cells while promoting regulatory CD4+ T-cell growth by expressing PD-L1 on their surface, secreting TGF-β and IL-10, and producing nitric oxide and arginase." (PMID 40869156, 2025). "In contrast to protumor cytokines such as IL-10 and TGF-β, abundant antitumor cytokines such as IL-12 and IFN-γ modulate the tumor microenvironment for immune activation." (PMID 41155253, 2025). "TAMs, for instance, secrete IL-10 and TGF-β, which inhibit anti-tumor immune responses, and the expression of immune checkpoint proteins like PD-L1 on cancer cells further dampens T cell function." (PMID 39861138, 2025).
tumor (continued). "Although we found some mild CD8+ T cell dependence of IL-6, IL-10, VEGF, and IL-1α in the tumor bed of LLCova-bearing mice, the biggest difference was evident in the proinflammatory cytokines IFN-γ and TNF-α." (PMID 40553564, 2025). "It is known that M2 macrophages release anti-inflammatory cytokines, including TGF-β, IL-10, Arginase-I and VEGF, to inhibit the immune response of tumor cells and promote the occurrence, progression and metastasis of tumor." (PMID 41145470, 2025). "Lidocaine suppressed IL-10 secretion in CD14+ tumor-infiltrating macrophages and CD4+CD25+ tumor-infiltrating Tregs." (PMID 40244064, 2025). "To evaluate the effects of oral probiotics CB and AKK on the immune response in 4 T1 tumor‐bearing mice, we measured the changes in levels of tumor necrosis factor (TNF‐α), IL‐6, and IL‐10 in both the tumors and serum of the mice." (PMID 40497373, 2025). "The microenvironment is characterized by various cellular phenotypes producing the anti-inflammatory cytokine interleukin-10 (IL-10), which facilitates persistent HPV infection and tumor progression." (PMID 40805127, 2025). "In particular, CAFs and M2 macrophages secrete TGF-β and IL-10, which promote immunosuppression, remodel the ECM, and support tumour malignancy." (PMID 41463127, 2025). "Meanwhile, a complex mixture of growth factors, cytokines, and chemokines, such as VEGF, IL-6, IL-10, and CCL2, facilitates crosstalk between tumor and stromal cells, promoting angiogenesis and immunosuppression." (PMID 41307758, 2025). "PAM-treated tumor lysates showed enhanced DC maturation, increased expression of CD83, CD86, and CD40, favorable cytokine profiles (IL-12/IL-10), and reduced expression of PDL1 and ILT-4." (PMID 41614820, 2025). "The secretion of IL-10 can contribute to the metabolic reprogramming of TAMs, stimulating downstream HIF-1α angiogenesis and tumor progression." (PMID 40361384, 2025). "Therefore, the treatment of macrophages before in vivo injection with tumor cells, as previously deployed, or the use of IL-10 conditional knockout models may represent other options required to further elucidate the specific mechanism of action and target of S3QEL 1.2." (PMID 39841829, 2025). "M2-like TAMs produce immunosuppressive cytokines (e.g., IL-10, TGF-β) and promote tissue remodeling and angiogenesis, supporting tumor progression." (PMID 40223940, 2025). "These M2-type TAMs secrete immunosuppressive cytokines, such as IL-10 and TGF-β, which inhibit the activity of effector T cells and NK cells, thereby facilitating tumor immune evasion." (PMID 40666095, 2025). "CGB5-expressing tumor cells convert conventional CD4+ T cells into Tregs by up-regulating the immunosuppressive cytokines TGF-β and IL-10, together with the transcription factor FOXP3." (PMID 41048937, 2025). "This pro-tumor property of Tregs is due to the secretion of molecules (TGF-β, IL-10, and IL-35) which regulate the expression of inhibitory receptors." (PMID 40376304, 2025). "This metabolic shift promotes an M2-like phenotype characterized by elevated immunosuppressive cytokine secretion (e.g., IL-10, TGF-β) and reduced anti-tumor immunity, as evidenced by decreased cytotoxic CD8+ T-cell infiltration." (PMID 41035647, 2025). "Conversely, alternatively activated M2-type tumor-associated macrophages (TAMs) suppress immune responses by producing factors such as IL-10 and TGF-β, and they promote tumor angiogenesis and metastasis." (PMID 41050671, 2025). "Neutrophils contribute to immune evasion by suppressing T-cell-mediated anti-tumor responses through the secretion of inhibitory cytokines like IL-10 and chemokines such as C-X-C motif chemokine ligand 8 (CXCL8), thereby facilitating tumor immune escape." (PMID 40565133, 2025). "In clear-cell renal cell carcinoma, macrophage-derived IL-23, promotes Treg expansion and elevates IL-10 and TGF-β expression, suppressing CTL-mediated tumor cell destruction." (PMID 40155378, 2025).
tumor (continued). "They secrete anti-inflammatory cytokines, including IL-10, TGF-β, CCL22, and CCL17, which support immune suppression and aid in tumor progression." (PMID 40867316, 2025). "A large number of cytokines, chemokines, and growth factors secreted by M2-TAMs, including TGF-β, PDGF, IL-6, IL-10, CXCL, COX-2, VEGF, and PDGF, favor angiogenesis and tumor progression." (PMID 40805183, 2025). "As a result, immunosuppressive TAMs accumulate in gliomas, where they secrete IL-10, TGF-β, arginase-1, and other factors that dampen T cell responses and support tumor growth." (PMID 41583439, 2025). "Further, this process is supported by the enhanced secretion of immunosuppressive cytokines, for example, IL-10 and TGF-β1 that promote tumor growth." (PMID 40625740, 2025). "IL-23 extended viral persistence through the up-regulation of IL-10, while its sustained expression and viral oncolysis enhanced chemokines and anti-tumor factors, making the TME more favorable for anti-tumor immunity." (PMID 40821119, 2025). "For example, interleukin-10(IL-10) stimulates regulatory (Treg) cells to further secrete IL-10 and also induces upregulation of the immune checkpoint protein PD-L1 in monocytes, which in turn reduces CD8+ T cell infiltration in the tumor microenvironment." (PMID 40124355, 2025). "The combined actions of IL-10 and IDO synergistically downregulate anti-tumor immunity in GBM, enabling immune evasion and promoting tumor progression." (PMID 40427130, 2025). "M28-CNVsHigh cells secreted increased levels of pro-tumor factors, such as PARC, VEGF, IL-10, and IL-8 and less secretion of anti-tumor factors." (PMID 40362334, 2025). "Regulatory T cells (Tregs) secrete immunosuppressive cytokines like IL-10 and TGF-β; IL-10 and TGF-β suppress anti-tumor immunity and promote tumor growth." (PMID 41375062, 2025). "Various tumor-derived factors induce differentiation of MDSCs in vitro, including PGE2, IL-6, IL-10, IL-1β, TGF-β, stem cell factor (SCF), and proangiogenic VEGF." (PMID 40940764, 2025). "Activated Tregs then secrete cytokines such as IL‐10 and TGF‐β, suppressing the cytotoxic and helper functions of effector T cells, thereby weakening immune surveillance and allowing tumour cells to escape." (PMID 41200753, 2025). "Next, we assessed the function of infiltrating effector T cells and Tregs in tumor tissues by detecting the levels of cytokines IFN γ, IL‐10, and TGF‐β in homogenates of the tumor tissues by enzyme‐linked immunosorbent assay (ELISA)." (PMID 39585774, 2025). "M2 TAMs secrete large amounts of IL‐10 in the TME, which stimulate JAK/STAT signaling in the tumor, lowers paclitaxel's effectiveness via the IL‐10/STAT3/Bcl‐2 cascade, and enhances paclitaxel resistance." (PMID 39927632, 2025). "CD11b+ Gr-1+ MDSCs inhibit T-cell activity through secretion of ​​interleukin-10 (IL-10) and TGF-β, facilitating tumour immune evasion." (PMID 41451221, 2025). "The interplay of the tumor-derived molecules like immune checkpoint ligands (PD-L1 and PD-L2), chemokines (CXCL9, CXCL10, and CXCL12), along with cytokines (TGF-β and IL-10), creates a complex immunosuppressive environment in EwS." (PMID 40242222, 2025). "This suggests that Foxp3, IL-10, and TGF-β1 collaboratively create an immune suppressive microenvironment by attracting immune suppressive cells and hindering anti-tumor immune cell infiltration." (PMID 41438510, 2025). "Tumor–stroma crosstalk (angiogenic signaling such as VEGF), recruitment of immunosuppressive cells, MHC-I downregulation, immunosuppressive cytokines (IL-10, TGF-β), and PD-L1 expression consolidate immune escape." (PMID 41463022, 2025). "This polarization is primarily driven by cytokines such as IL-10 and TGF-β, secreted by tumor and stromal cells, redirecting macrophage function away from initiating anti-tumor immune responses." (PMID 40003906, 2025).